DLEU1 (deleted in lymphocytic leukemia 1)
Diseases named in the same sentence as DLEU1 in open-access papers (continued):
Sharing a sentence is not in itself a finding about the gene and the disease.
tumor (continued). "Immunohistochemical analysis revealed that Ki-67 expression was decreased in tumors treated with the DLEU1 siRNA, which indicates DLEU1 knockdown suppresses tumor cell proliferation." (PMID 30069008, 2018). "Our data proved that DLEU1 knockdown significantly inhibited cell proliferation both in vitro and in vivo, whereas overexpressing DLEU1 promoted tumor growth." (PMID 30098595, 2018). "DLEU1 has been found frequently deleted and a potential tumor suppressor gene in hematopoietic tumors including chronic lymphocytic leukemia (CLL) and mantle cell lymphoma." (PMID 28427156, 2017). "More importantly, the deletion of DLEU1 results in significant enhancement of tumor progression and shortened survival in RTX and CTX treated DLEU1 KD cells xenografted mice compared to WT cell injected mice." (PMID 28427156, 2017). "This could potentially establish a positive feedback loop that further amplifies DLEU1 expression, possibly contributing to tumor cell adaptation or resistance." (PMID 41484982, 2026). "Similarly, in a mouse xenograft model, DLEU1 knockdown synergistically enhanced Etoposide-induced tumor suppression, leading to a significantly greater reduction in tumor volume and weight compared to the shNC group." (PMID 41484982, 2026). "SNHG14 exhibits oncogenic properties in CRC, and DLEU1 demonstrates tumor suppressive functions." (PMID 41378121, 2025). "For example, lncRNA deleted in lymphocytic leukemia 1 (DLEU1) promotes granulosa-like tumor cell line (KGN) apoptosis by sponging miR-146b-5p, while lncRNA X-inactive specific transcript (XIST) induces KGN cells apoptosis via the miR-30c-5p/Bcl2-like protein 11 signaling axis." (PMID 40175717, 2025). "We found that RBM8A may compete with DLEU1 for binding to miR-128-1-5p, and aberrant RBM8A expression was associations with tumor infiltration by immune cells." (PMID 35573726, 2022). "DLEU1 knockdown or cisplatin treatment alone was sufficient to impair tumor growth." (PMID 35619131, 2022). "For in vivo experiments, DLEU1 knockdown repressed tumor volumes and tumor weights, but cotransfected antagomir-149-5p could partly save the inhibitory function of silencing DLEU1 in vivo." (PMID 35864972, 2022). "Moreover, compared with cisplatin alone, the combination of cisplatin and DLEU1 knockdown exhibited a stronger inhibitory effect on xenograft tumor growth in nude mice." (PMID 35619131, 2022). "Functionally, both CKAP2 and HIF-1α at least partially mediated the pro-tumor activities of DLEU1." (PMID 35853854, 2022). "DLEU1 is a potential tumor-related lncRNA and abnormally expressed in multiple cancers." (PMID 35864972, 2022). "Because DLEU1 overexpression promoted tumor growth, which made us difficult to judge whether DLEU1 could enhance chemo-resistance in vivo from the absolute tumor volumes and weights." (PMID 35864972, 2022). "DLEU1 inhibition markedly repressed tumour size, growth and weight compared to sh-NC group." (PMID 34113562, 2021). "Moreover, up regulation of DLEU1 enhanced tumor growth and aggressiveness and induced cisplatin resistance through HS3ST3B1 induction." (PMID 33183321, 2020). "Finally, as reported in methods, we overlapped these lists, in order to obtain a set of potential tumor-suppressor lncRNAs (i.e., DLEU1, LINC00261, LINC00483, LINC01207, MCF2L-AS1) and oncogene lncRNAs (MEG3, RUNX1-IT1, and TP73-AS1) to experimentally analyze." (PMID 33552987, 2020). "DLEU1 knockdown significantly inhibited tumour growth in nude mice compared to sh‐NC group." (PMID 31207081, 2019). "We also examined the expression of DLEU1 and miR‐133a in xenograft tumours." (PMID 31207081, 2019). "Furthermore, we showed that DLEU1 executes its tumor-promoting functions by sponging tumor suppressor miR-99b and increasing the protein expression of oncogene HS3ST3B1 in BCA." (PMID 30984249, 2019). "Also, knockdown of DLEU1 evidently impaired tumour size (Figur7B) and weight in contrast with sh‐NC group." (PMID 31207081, 2019).
tumor (continued). "Taken together, these results showed that DLEU1 suppressed tumor growth in vivo." (PMID 30098595, 2018). "Besides, we found that the expression of DLEU1 in CRC was positively correlated with tumor clinical stage through ISH." (PMID 30098595, 2018). "We found that DLEU1 was remarkably up-regulated in CRC tissues compared to non-tumor tissues." (PMID 30098595, 2018). "We found that CRC samples displayed higher expression of DLEU1 than non-tumor tissues." (PMID 30098595, 2018). "We found that DLEU1 knockdown significantly delayed tumor growth in vivo." (PMID 30098595, 2018). "Nude mouse xenograft assay demonstrated that DLEU1 overexpression promoted tumour growth in vivo." (PMID 28598010, 2017). "Moreover, we observed that DLEU1 could inhibit the apoptosis of ESCC cells but had little effect on the cell cycle, indicating that DLEU1 plays a significant role in promoting tumor growth mainly by inhibiting cell apoptosis." (PMID 35619131, 2022). "Furthermore, DLEU1 knockdown impaired tumour growth in vivo by regulating miR‐133a/IGF‐1R axis." (PMID 31207081, 2019). "However, the potential roles of DLEU1 in CESC remain unclear, and our analysis revealed that DLEU1 may also exert as a tumor suppressor in CESC." (PMID 30662454, 2018). "Targeting the DLEU1/ASCC2/G6PD axis significantly suppresses GC cells proliferation and tumor growth, proposing a therapeutic strategy targeting this pathway." (PMID 41484982, 2026). "Functionally, co-targeting DLEU1 and ASCC2 synergized with G6PD inhibition, significantly impairing GC cells viability and tumor growth." (PMID 41484982, 2026). "Functionally, dual silencing of DLEU1 and ASCC2, in combination with G6PD inhibition, synergistically suppressed the viability of GC cells and tumor growth in vivo, highlighting the therapeutic potential of targeting the DLEU1/ASCC2/G6PD axis." (PMID 41484982, 2026). "This included DLEU1, which was hypomethylated in FAP versus normal colon organoids, but significantly hypermethylated in all three tumor vs NAT analyses." (PMID 35999641, 2022). "DNA demethylation level was positively correlated with the expression of DLEU1 and DLEU2, albeit negatively with the expression of neighboring tumor-suppressors, suggesting in cis co-regulation of these genes and their functional connection." (PMID 36362925, 2022). "DLEU1 is upregulated in GBM, and its knockout inhibits GBM cell proliferation and apoptosis, while sensitizing tumor cells to temozolomide." (PMID 35573726, 2022). "DLEU1 is frequently overexpressed in OSCC cell lines, and its knockdown strongly suppresses proliferation, migration, invasion, and in vivo tumor formation by OSCC cells." (PMID 34650128, 2021). "DLEU1 knockdown suppresses in vitro PTC cell proliferation and invasion, and inhibits xenograft tumor growth in the nude model mice." (PMID 32910787, 2020). "By contrast, DLEU1 is overexpressed in epithelial ovarian carcinoma (EOC), where it contributes to tumor development through direct interaction with miR-490-3p29." (PMID 30069008, 2018). "DNA-demethylation of the regions D6 and E6 in CLL cells is directly correlated with an increase in the expression of DLEU1 and DLEU2 and inversely correlated with the expression of the neighboring candidate tumor suppressing protein-coding genes." (PMID 23593011, 2013). "We investigated the expression and clinical significance of DLEU1 in GC by analyzing its mRNA levels in tumor and adjacent non-cancerous tissues from patients in the FUSCC cohort." (PMID 41484982, 2026). "Besides DLEU1 and DLEU2, tumor-suppressor mechanisms at 13q14.3 involve several protein-coding tumor suppressor genes and pathogenesis of CLL probably results from concerted action of these elements." (PMID 36362925, 2022). "Indeed, it has been demonstrated that DLEU1 and DLEU2 and their neighboring tumor-suppressor genes are epigenetically deregulated in the majority of CLL patients." (PMID 36362925, 2022).
tumor (continued). "Our results showed that the lncRNA DLEU1 was closely related to tumor proliferation and migration, while IT1 had no candidate peptides encoding ORFS." (PMID 33735310, 2021). "DLEU1 is a nonprotein-coding RNA gene that was originally identified as a potential tumor suppressor gene." (PMID 32637184, 2020). "miR-490-3p acts as a tumor suppressor by targeting CDK1 in EOC, and DLEU1 may promote tumorigenesis by inhibiting miR-490-3p function." (PMID 30069008, 2018). "To further examine whether DLEU1 regulated CRC development and progression by activating KPNA3, we analyzed the expression of KPNA3 in CRC tissues and non-tumor tissues." (PMID 30098595, 2018). "Interestingly, we found that knockdown of DLEU1 significantly inhibited DLEU1 expression, increased miR‐133a expression, and inhibited IGF‐1R expression and its downstream PI3K/AKT pathway in xenograft tumours." (PMID 31207081, 2019). "Moreover, hsa-miR-532-5p, RBM38, EGLN1, and DLEU1 were demonstrated as both oncogenes and tumor-suppressors in non-CESC cancers and their roles in CESC were unclear." (PMID 30662454, 2018).
cancer (33 papers, 2014 to 2026). A tumor composed of atypical neoplastic, often pleomorphic cells that invade other tissues. "DLEU1 has been implicated in the development and progression of several cancers, including GBM." (PMID 35573726, 2022). "Independent validation via the GEPIA2 database confirmed DLEU1 upregulation in six cancer types and its correlation with poorer survival." (PMID 42052445, 2026). "In a study on the correlation between DLEU1 and CC, some researchers found that DLEU1 was highly expressed in CC cancer tissues and cancer cells." (PMID 39687982, 2025). "DLEU1 play an important role in the proliferation, migration, invasion, and inhibition of apoptosis of cancer cells." (PMID 37543428, 2023). "lncRNA DLEU1 can inhibit CRC cell growth, motility, and invasion, indicating the relevance of the DLEU1/SMARCA1/KPNA3 axis in the etiology of this cancer type." (PMID 37280524, 2023). "Taken together, DLEU1 acts as a cancer-promoting gene and exhibits pivotal function in CCA progression." (PMID 35864972, 2022). "In contrast, increasing studies focusing on DLEU1 presented convincing evidence that DLEU1 is a pan-cancer oncogene." (PMID 35853854, 2022). "An earlier study has suggested that higher DLEU1 expression is a pan-cancer marker for worse prognosis." (PMID 35853854, 2022). "Rescue experiments confirmed that the cancer-promoting effect of DLEU1 was saved by interfering miR-149-5p or YAP1." (PMID 35864972, 2022). "The lncRNA deleted in lymphocytic leukemia 1 (DLEU1) located on chromosome 13q14.3 has been reported to be abnormally expressed in many cancers." (PMID 34113562, 2021). "DLEU1 is aberrantly overexpressed in a variety of tumors and contributes to tumorigenesis and cancer development." (PMID 30984249, 2019). "Mounting studies have revealed that long non-coding RNA (lncRNA) deleted in lymphocytic leukemia 1 (DLEU1) positively regulated the initiation and development of various human malignant tumors." (PMID 31713587, 2019). "Then in a series of 29 samples of primary OSCC tissue and 17 adjacent normal tissue samples obtained from Japanese patients, we observed that DLEU1 expression is significantly elevated in cancer tissues." (PMID 30069008, 2018). "In line with our findings, a recent report suggests that decreased DNA methylation and increased histone modifications may contribute to DLEU1 upregulation in cancer." (PMID 35619131, 2022). "Second, are there any cancer-related targets other than CKAP2 co-regulated by DLEU1 and HIF-1α?" (PMID 35853854, 2022). "However, recent studies reveal oncogenic activities of DLEU1: it is up-regulated in a panel of human cancers, correlates with worse prognosis, and promotes various malignant phenotypes." (PMID 35853854, 2022). "Besides, DLEU1 is also found to be highly expressed in osteosarcoma, glioblastoma multiforme and hepatocellular carcinoma, and aggravates cancer progression." (PMID 34113562, 2021). "DLEU1 has been reported to interact with miRNAs to regulate gene expression in various cancers." (PMID 34113562, 2021). "Microarray analysis revealed that DLEU1 may regulate expression of a number of cancer-related genes." (PMID 30069008, 2018). "Taken together, YY1/DLEU1/miR-149-5p/YAP1 axis exerts crucial cancer-promoting function in CCA progression, and DLEU1 has potentiality as a biomarker or therapeutic target." (PMID 35864972, 2022). "DLEU1 can act as a competitive endogenous RNA that promotes elevated TRAF4 expression levels, promotes cancer cell proliferation through the Hippo signaling pathway and Wnt/β-catenin signaling pathway and regulate cell migration." (PMID 35242717, 2022). "Four of the most frequently overexpressed lncRNAs in cancer tissues, namely, LINC01614, LOC284930, KCNMB2-AS1, and DLEU1, were selected for functional analysis." (PMID 35619131, 2022). "DLEU1 activates KPNA3, which is related to the increased proliferation and migration of cancer cells." (PMID 33735310, 2021).
cancer (continued). "In our study, we found that DLEU1 interacted with SMARCA1 directly in CRC cells and regulated cancer cell proliferation." (PMID 30098595, 2018). "Microarray analysis revealed that DLEU1 knockdown significantly affects expression of a number of cancer-related genes in OSCC cells, including HAS3, CD44, and TP63, suggesting that DLEU1 regulates HA-CD44 signaling." (PMID 30069008, 2018). "qRT-PCR performed to validate the microarray results showed that expression of a number of cancer-related genes, including HAS3, CD44, TP63, and SMYD2, was decreased by siRNAs targeting DLEU1, while expression of CDH1 was increased by DLEU1 knockdown." (PMID 30069008, 2018). "The lncRNAs DLEU1 and DLEU2 at 13q14.3 are often deleted in multiple types of cancers, and DLEU1 and DLEU2 modulate nuclear factor B function by down-regulating the transcription of their neighboring protein-coding KPNA3 and the microRNAs miR-15 and miR-16." (PMID 24586304, 2014). "While DLEU1 acts as an oncogene in these cancers, its regulatory mechanism and biological role in PTC is not clear." (PMID 32910787, 2020). "To test whether DLEU1 exerts oncogenic functions in BCA by modulating the miR-99b/HS3ST3B1 axis, we investigated the effects of miR-99b or HS3ST3B1 on DLEU1-induced cancer cell proliferation, invasion, and cisplatin resistance." (PMID 30984249, 2019). "To unravel the mechanism of DLEU1 up-regulation in GBM, we utilized bioinformatics prediction tools (UCSC and JASPAR) since transcription factor has been reported to promote lncRNA’s expression by acting as a transcription activator in cancers." (PMID 31713587, 2019). "The most significant of these findings corresponded to the genomic region containing Deleted in lymphatic leukemia 1 (DLEU1, FDR = 3.08E−22), which was hypomethylated in FAP and has previously been described as a tumor suppressor gene in non-CRC cancers." (PMID 35999641, 2022).
DLEU1 also shares sentences with these, for which no sentence is quoted: non-small cell lung carcinoma (4 papers); Burkitt lymphoma (3); hematologic malignancies (3); liver cancer (2); spindle cell lipoma (2); benign ovarian tumours (1); clear cell renal cell carcinoma (1); diffuse large B-cell lymphoma (1); lymphoma (1); metastasis (1); metastatic prostate carcinoma (1); multiple sclerosis (1); nasopharyngeal carcinoma (1); Nephroblastoma (1); osteoporosis (1); sarcopenia (1); triple-negative breast carcinoma (1).